MDM2 (MDM2 proto-oncogene)
Diseases named in the same sentence as MDM2 in open-access papers (continued):
Sharing a sentence is not in itself a finding about the gene and the disease.
tumor (continued). "We analyzed the main pathogenic pathways (MDM2 and CDK4), as well as the tumor microvascularization (CD31 and CD34) by immunohistochemical tests." (PMID 38132190, 2023). "In this study, we aimed to shed further light on the prevalence and putative tumor biological function of MDM2 in GC and studied protein expression and gene amplification in a large and well-characterized cohort of Western patients with GC." (PMID 37821635, 2023). "The median protein concentrations of E2F2, MDM2 and p16 were higher in the tumour tissue than in the margin samples." (PMID 37185737, 2023). "MDM2 inhibitor APG-115 was reported to enhance the efficacy of PD-1 blockade via increasing anticancer immunity in the tumor microenvironment." (PMID 37215134, 2023). "Sometimes a tumor can have extra copies of certain genes, both of which contain multiple copies of MDM2." (PMID 37297833, 2023). "To examine the synthetic lethal effect of MDM2 inhibitor in vivo, we conducted tumor xenograft experiments in mice bearing HCT116 PTEN+/+and PTEN-/- CRC tumors." (PMID 37496993, 2023). "In a preclinical study using tumour xenograft model, AMG‐232 effectively inhibited tumour growth and completely repressed MDM2‐amplified SJSA‐1 via cell cycle arrest and apoptosis." (PMID 36881608, 2023). "Further investigations of the complex MDM2/MDM4 motif, and its contribution to the tumor microenvironment and observed associations, are warranted." (PMID 37345045, 2023). "Especially researchers who are interested in TIL-based adopted immunotherapy should exclude these cells in their primary tumor models, e.g. by MDM2-inhibitor treatment." (PMID 36639629, 2023). "The dedifferentiated tumour areas showed positive MDM2 and CDK4 staining within neoplastic cells, with the Ki 67 proliferation marker expressed in approximately 10% of the cells." (PMID 37241198, 2023). "The median MDM2 gene expression was 0.371 (0.165–0.705) in the tumour samples and 0.555 (0.274–0.989) in the margin samples." (PMID 38002053, 2023).
tumor (continued). "p27 is a protein downstream of MDM2 that acts as a tumor suppressor, while p21 is a protein able to bind MDM2, thus increasing antitumor activity and apoptosis." (PMID 36672146, 2023). "This is the first study to evaluate the levels of E2F2, MDM2 and p16 in the primary OSCC tumour and the matching margin samples and their association with the selected sociodemographic and clinicopathological characteristics." (PMID 37185737, 2023). "BI 907828 significantly inhibited tumor growth in two mouse models of DDLPS harboring amplifications of MDM2, compared with doxorubicin and control groups." (PMID 37297833, 2023). "In this way, there is a significant relationship between higher MDM2 expression and the potential for the formation of tumor metastasis." (PMID 37049742, 2023). "Astragalus membranaceus was reported to reduce MDM2 levels in tumor cells and had an anti-tumor effect." (PMID 36673369, 2023). "In preclinical models of GBM, MDM2 inhibitors can reduce tumor growth, prolong survival, and enhance the cytotoxicity of RT when used in combination." (PMID 37509518, 2023). "In vivo and in intro experiments both showed that the MDM2 inhibitor etoposide relieved the tumor proliferation and migration of NF-PitNETs by inhibiting the activity of MDM2." (PMID 36837574, 2023). "The median protein concentrations of MDM2 were higher in the tumour tissue than in the margin samples." (PMID 37185737, 2023).
tumor (continued). "MDM2 is one of the genes that we found; by inhibiting MDM2 in human desmoid tumors, it decreases the proliferation of desmoid tumor cancer cells." (PMID 37297833, 2023). "There was less suppression of tumor growth in mice with MDM2 and S100A6 co-transfected cells than in those with S100A6-transfected cells." (PMID 37217945, 2023). "First, the mRNA level of the MDM2 gene was assessed in a large sample size of HNSCC tumor samples (519 samples) compared to normal tissues (44 samples) using data from TCGA and GTEx in GEPIA." (PMID 37081989, 2023). "Using this method, human T-cell clones with high affinity for tumor-associated antigens, such as cyclin D1, WT1, and MDM2, were isolated, and these high-affinity TCR genes were cloned into vectors for gene therapy." (PMID 37649123, 2023). "Our experimental results also suggested that silencing MDM2 mimics the tumor-suppressive activity of miR-590-3p in HepG2 cells, indicating that miR-590-3p plays a tumor-suppressor role in HepG2 by targeting MDM2." (PMID 37138218, 2023).
tumor (continued). "Extensive preclinical research has been conducted with MDM2 inhibitors and has demonstrated varying efficacy rates in vitro and in vivo in multiple experimental tumor models." (PMID 37509518, 2023). "In order to explore the putative tumor biological significance, we correlated both, MDM2 expression and MDM2 amplification, with diverse clinicopathological patient characteristics." (PMID 37821635, 2023). "Multivariate analysis considering patient characteristics, tumor characteristics, and MDM2 levels showed that MDM2 was an independent prognostic factor that was statistically significantly correlated with complete response to ILP (p = 0.04)." (PMID 38138884, 2023). "Based on several studies, it can be assumed that miRNAs directly target the MDM2 gene to regulate tumour progression." (PMID 38002053, 2023). "Despite tumor regrowth, tumors continued to respond to MDM2 combined with MEK inhibition upon rechallenge." (PMID 35075200, 2022). "As a result, MDM2 KO xenografts were substantially smaller than those with WT MDM2, and the tumour growth curve of the mice bearing KO xenografts showed a remarkable retarded growth compared with mice in the control group." (PMID 35692096, 2022).
tumor (continued). "In OS, circ-SAMD4A is reported to facilitate OS progression by up-regulating MDM2 via sponging miR-1244, suggesting the tumor suppressor role of miR-1244 in OS." (PMID 36109749, 2022). "FISH visualization was used to detect MDM2 amplification in the primary tumor and P1-P4 PDXs of patient Case702." (PMID 35928724, 2022). "Only the FISH method was needed for MDM2 analysis or when the material was limited (e.g., in a biopsy sample with few tumour cells, the FISH analysis requires only one section of 3 μm compared to 2 × 10 μm for c/qRT–PCR)." (PMID 36614077, 2022). "Here, to investigate the mechanism by which PPM1D blocks tumor cell death upon MDM2 inhibition, we employed papillary thyroid carcinoma cell lines expressing high levels of wild type PPM1D34." (PMID 36456590, 2022). "Based on this, we can conduct further research such as the combination of MDM2 inhibitors with other drugs, screening beneficial patients, which will contribute to the personalized tumor treatment, especially for RLPS patients." (PMID 35928724, 2022). "MDMX (also called MDM4), a homolog of MDM2, can also bind to and promote RB degradation in an MDM2-dependent manner, thereby promoting tumor growth." (PMID 36230664, 2022). "A FISH test performed on the dedifferentiated component of the tumor that was surgically removed 8 months after the initial diagnosis was positive for MDM2 amplification." (PMID 34986184, 2022). "For example, the splicing type of Ras and CyclinD1 determines the rate of tumor cell proliferation, PKM alternative splicing changes the type of metabolism, and MDM4 and MDM2 protein isoforms regulate tumor sensitivity to therapy." (PMID 35538281, 2022). "Pharmacological induction of eIF2α phosphorylation synergizes with MDM2 inhibition to induce cell death and halt tumor growth in mice." (PMID 36456590, 2022). "The tumorigenic potential of MDM2 was further demonstrated by its ability to transform rodent fibroblasts, and to promote tumor formation and progression in nude mice or Eu-myc transgenic mice." (PMID 35625571, 2022). "Preclinical and clinical studies have demonstrated promising results in which MDM2 inhibitors induced growth inhibition or tumor regression." (PMID 35075200, 2022). "Our study reveals that ABCA6 acts as tumor suppressor in EWS cells via cholesterol-mediated inhibition of IGF1R/AKT/MDM2 signaling, which promotes the pro-apoptotic effects of doxorubicin and reduces cell migration." (PMID 36149602, 2022).